MYCN (MYCN proto-oncogene, bHLH transcription factor)
Diseases named in the same sentence as MYCN in open-access papers (continued):
Sharing a sentence is not in itself a finding about the gene and the disease.
neuroblastoma (continued). "MYCN amplification is regarded as an initiating event that drives the development of high-risk neuroblastomas." (PMID 33324552, 2020). "As the chemotherapeutic protocol for neuroblastomas varies by risk group, accurate information on the MYCN status, pathological status of differentiation, and genetic aberration is necessary to ensure adequate treatment." (PMID 32522190, 2020). "While MYCN amplification is prevalent in high-risk neuroblastoma and some other pediatric cancers, and is an important biomarker for patient outcomes, it remains an elusive drug target." (PMID 32211329, 2020). "It is a well-known risk factor of neuroblastoma, and MYCN amplification is associated with poor diagnosis and survival." (PMID 32629858, 2020). "As a representative model, we selected two patient-derived xenograft (PDX) cultures from two high-risk patients with MYCN amplified neuroblastoma, termed NB-PDX2 and NB-PDX3." (PMID 31900415, 2020). "In particular, MYCN is an oncogenic driver, and MYCN amplification is found in ~40–50% of high-risk neuroblastoma and associated with poor outcomes." (PMID 32983125, 2020). "We sought to validate our case‐control analyses suggestive of an association between genetic contributions to stature and MYCN‐amplified neuroblastoma risk using additional genotype‐phenotype datasets." (PMID 32945147, 2020). "The majority of ctDNA studies in neuroblastoma are based on digital droplet PCR or targeted sequencing that require prior characterization of the biomarkers such as MYCN amplification and activating ALK mutations." (PMID 33381456, 2020). "This includes ALKF1174 and ALKR1275 mutations and MYCN amplifications in primary neuroblastomas, the BRAFV600E mutation in Langerhans cell histiocytosis, and EWSR1 translocations in Ewing sarcoma, to name a few." (PMID 31897843, 2020). "To analyze the epigenomic landscape in ATRX-mutant neuroblastoma cells, compared with that in wild-type ATRX neuroblastoma, we selected eight cell lines that encompass the major genetic groups, including those with MYCN amplification or ATRX mutations." (PMID 32060267, 2020). "Previous studies demonstrated that the expression of SLC19A1, the gene encoding the RFC-1 receptor, is associated with MYCN amplification in neuroblastoma." (PMID 32850011, 2020). "It has been demonstrated that genomic amplification of the MYCN oncogene by promoting SEs causes upregulation of the active transcriptional program of neuroblastoma (NB) cells and sensitizes NB cells to the inhibition of CDK7." (PMID 32128448, 2020). "A previous study found that MYCN amplification is one of the most significant prognostic indicators of neuroblastoma and is associated with rapid tumor progression and poor prognosis." (PMID 33381457, 2020). "The purpose of this study was to determine the transcription factors and signaling pathways associated with MYCN amplification and identify the prognostic relevance of MYCN associated genes in neuroblastoma." (PMID 32593299, 2020). "An increase in the polygenic score for childhood stature, corresponding to a ~0.5 cm increase in pre‐pubertal height, was associated with greater risk of MYCN‐amplified neuroblastoma (OR = 1.14, P = .047)." (PMID 32945147, 2020). "By conferring stem-like qualities such as infinite self-renewal, apoptotic resistance or metabolic flexibility, MYCN contributes to the life-threatening characteristics of high-risk neuroblastoma." (PMID 33585251, 2020). "These shared biological pathways and the genetic architecture underlying both growth trajectories and risk of MYCN‐amplified neuroblastoma require additional investigation." (PMID 32945147, 2020).
neuroblastoma (continued). "To date, targeting MYCN, a well-established driver gene in high-risk neuroblastoma, is still challenging." (PMID 33324552, 2020). "Transcription factor E2F1 was up-regulated by MYCN amplification and associated with the poor prognosis of neuroblastoma." (PMID 32593299, 2020). "We used SuperHistopath to quantify the phenotype of MYCN-driven transgenic mouse models of high-risk stroma-poor neuroblastoma." (PMID 33552964, 2020). "Here we show that ATRX mutations and MYCN amplification are mutually exclusive across all ages and stages in neuroblastoma." (PMID 32060267, 2020). "Clinical observation of MYCN amplification in human neuroblastoma firstly pointed out the potential association between MYCN gene and tumorigenesis." (PMID 33614505, 2020). "The causative variants and biologic mechanisms linking these risk loci to neuroblastoma pathogenesis, and MYCN‐amplified tumorigenesis specifically, remain an active area of investigation." (PMID 32945147, 2020). "Increased NME1 gene copy number has been directly identified in 14%–23% of neuroblastoma tumors, and increased NME1 expression has also been identified in high-risk neuroblastoma tumors, possibly secondary to MYCN-mediated regulation of NME1 expression." (PMID 32392889, 2020). "A major molecular alteration in neuroblastoma is the amplification of the locus encoding the oncogenic transcription factor MYCN." (PMID 31900399, 2020). "One example where this is true is MYCN amplification, which is causatively linked to neuroblastoma outcome, in a manner that depends on mRNA expression." (PMID 31900415, 2020). "In general, patients with stage 4 disease and older than 18 months at diagnosis or with greater than stage 1 MYCN-amplified neuroblastoma are classified as high-risk neuroblastoma (HR-NB)." (PMID 32629858, 2020). "Activating ALK mutations combined with MYCN amplifications in neuroblastoma is associated with very poor prognosis in patients, which is mirrored by the finding that ALK mutation accelerates tumour formation in animal models of MYCN-driven neuroblastoma." (PMID 31937834, 2020). "In TARGET and GSE85047 datasets, neuroblastoma patients with MYCN amplification were associated with worse prognosis." (PMID 32593299, 2020). "We also identified the functional signaling pathways which were associated with MYCN amplification in neuroblastoma." (PMID 32593299, 2020). "Retinoid repression of MYCN transcription was a major motivation for the inclusion of 13 cis-retinoic acid during the consolidation phase of treatment for high-risk neuroblastomas." (PMID 33628735, 2020). "In order to elucidate novel RBPs involved in MYCN-amplified and other high-risk neuroblastoma subtypes, we performed differential mRNA expression analysis of RBPs in a large primary tumour cohort (n = 498)." (PMID 32707690, 2020). "Here we demonstrate that the DNA-replicative stress induced by ATRX mutations and MYCN amplification cause synthetic lethality in neuroblastoma." (PMID 32060267, 2020). "One of the well-characterized mechanisms that lead to MYCN overexpression in neuroblastoma is MYCN gene amplification, which is observed in 25% of neuroblastomas and is associated with poor patient prognosis." (PMID 32087738, 2020). "Polygenic score analyses revealed that each 0.5 cm increase in genetically predicted childhood height attainment prior to puberty was associated with a 1.14‐fold increase in risk of MYCN‐amplified neuroblastoma." (PMID 32945147, 2020). "An increase in the polygenic score for adult stature, corresponding to a ~1.7 cm increase in adult height attainment, was associated with decreased risk of MYCN‐amplified neuroblastoma (OR = 0.87, P = .047)." (PMID 32945147, 2020). "According to the International Neuroblastoma Risk Group, neuroblastoma patients are classified into low, intermediate or high risk subgroups based on MYCN amplification status." (PMID 32593299, 2020).
neuroblastoma (continued). "Tumor-Associated Macrophages (TAM) are strictly associated with poor survival in neuroblastomas that lack MYCN amplification." (PMID 32244473, 2020). "MYCN‐amplification is consistently associated with an aggressive neuroblastoma phenotype and poorer clinical outcomes." (PMID 32945147, 2020). "This risk classification is based on age at diagnosis, MYCN amplification status, International Neuroblastoma Staging System (INSS) stage, histopathology and tumour cell ploidy." (PMID 32683778, 2020). "Over 50% of patients with neuroblastoma are considered to have ‘high risk’ disease, because of adverse prognostic features such as amplification of the MYCN oncogene or metastatic spread." (PMID 33028899, 2020). "International Neuroblastoma Risk Group (INRG) defines the high-risk group to include patients with MYCN amplified tumours and patients > 18 months old with metastatic tumours." (PMID 33172452, 2020). "The association between MYCN amplification and folate metabolism suggests the potential role of antifolate drugs in the treatment of neuroblastomas." (PMID 32850011, 2020). "The undruggable nature of oncogenic Myc transcription factors poses a therapeutic challenge in neuroblastoma, a pediatric cancer in which MYCN amplification is strongly associated with unfavorable outcome." (PMID 33016930, 2020). "In high-risk neuroblastoma patients, if amplification of MYCN occurs it is always present at diagnosis." (PMID 33585251, 2020). "In neuroblastoma, folate mediated one-carbon metabolism is associated with aggressiveness and MYCN amplification." (PMID 32850011, 2020). "On the contrary, neuroblastoma, a tumor with neural origin like retinoblastoma seems to behave differently as in MYCN-amplified neuroblastomas diploidy is associated with a poorer outcome than hyperdiploidy." (PMID 32971811, 2020). "For example, ~19% of high-risk neuroblastomas have MYCN amplification and high MYCN expression, whereas ~11% overexpress MYC and less than 0.5% highly express both." (PMID 33425720, 2020). "Together, these data suggest that in some high-risk neuroblastomas that lack MYCN amplification, MYC can drive CAMKV transcription." (PMID 32211329, 2020). "Increased levels of oncogene-induced RS are considered as a hallmark of neuroblastoma with MYCN amplification, a prominent predictive marker of unfavorable prognosis." (PMID 33014050, 2020). "Amplification of the MYCN oncogene is present in 18–20% of all neuroblastomas (40% of high-risk neuroblastomas) and is an adverse prognostic factor." (PMID 33628735, 2020). "Here we determined that expression of miR-145, another potential tumor suppressor in neuroblastoma, was significantly lower in high-risk MYCN amplified tumors and that lower miR-145 expression was associated with worse EFS and OS in our patient cohort." (PMID 32083506, 2020). "As the drive alteration in neuroblastoma, prognostic signature associated with MYCN amplification was previously identified." (PMID 32593299, 2020). "High-risk neuroblastoma is defined by metastatic disease over the age of 18 months or MYCN amplification at any age." (PMID 33324208, 2020). "This is in keeping with a recent publication also showing that ATRX mutations and MYCN amplification are synthetically lethal in neuroblastoma." (PMID 32375866, 2020). "Most importantly, the therapeutic ADC induced complete eradication of subcutaneous tumour masses, considerably prolonging survival, of mice transplanted with patient-derived high-risk neuroblastomas with MYCN amplification." (PMID 33076448, 2020). "Previous studies have demonstrated that SLC19A1 is associated with MYCN amplification in neuroblastoma and that SLC19A1 is a direct transcriptional target of N-myc." (PMID 32850011, 2020). "Since MYCN amplification was associated with poor outcome in neuroblastoma, we next assessed the prognostic effects of the 13 MYC target genes which were up-regulated in MYCN amplified neuroblastoma." (PMID 32593299, 2020).
neuroblastoma (continued). "Amplification of the MYCN oncogene is found in almost 40% of clinical high-risk neuroblastomas, and is associated with up-regulation of TERT expression and telomere dysfunction." (PMID 32375866, 2020). "Our results also implicate that the pharmacologic inhibition of BRD4 by ARV-825 caused a reduction in MYCN or c-Myc mRNA and protein expression in neuroblastoma." (PMID 33324552, 2020). "NME1 expression is also higher in tumors with MYCN oncogene amplification and in tumors from patients with stage 4 disease, consistent with its association with more aggressive neuroblastoma tumors." (PMID 32392889, 2020). "In neuroblastoma, the most common extracranial pediatric solid tumor, MYCN amplification is an important clinical biomarker associated with poor prognosis." (PMID 32310340, 2020). "Our study is unique in its approach to dissecting a role for genetic determinants of height in contributing to neuroblastoma risk overall and MYCN‐amplified neuroblastoma in particular." (PMID 32945147, 2020). "The majority of high-risk neuroblastomas can be divided into three distinct molecular subgroups defined by the presence of MYCN amplification, upstream TERT rearrangements or alternative lengthening of telomeres (ALT)." (PMID 32375866, 2020). "Our analysis of publicly available gene expression RNAseq and microarray data, show that high-risk neuroblastoma with high MYCN expression strongly correlates to elevated expression of genes involved in ribosome biogenesis and poor patient survival." (PMID 30542116, 2019). "Consistent with this, previous studies have reported that neuroblastomas (NBs) with MYCN amplification, the most common diagnostic marker of NB with unfavorable histology, are sensitive to CHK1is." (PMID 31362335, 2019). "The most significant adverse risk factor for neuroblastoma (NB) is MYCN gene amplification, which strongly associates with high-risk disease." (PMID 31365300, 2019). "Around 50% are high-risk neuroblastoma (HRNB) defined as unresectable or metastatic tumours with amplification of the MYCN oncogene in any age group or those over 18 months with metastatic disease." (PMID 30822684, 2019). "The most frequent chromosomal aberration associated with poor prognosis in neuroblastoma is somatically acquired amplification of the MYCN gene, hemizygous deletions of 1p and 11q, and segmental gain of 17q." (PMID 30760980, 2019). "In our experiments, the data on ELOVL2 presented here identify that declined DHA synesis caused by MYCN-mediated ELOVL2 inhibition in neuroblastoma cells contributes to tumor aggressiveness." (PMID 31856871, 2019). "The malignancy of neuroblastoma correlates with the amplification of MYCN, which encodes the transcription factor N-Myc." (PMID 30836897, 2019). "A molecular hallmark of high-risk neuroblastoma is genetic amplification and high expression of the MYCN oncogene." (PMID 30542116, 2019). "Genome-wide studies revealed several recurrent molecular abnormalities in primary neuroblastoma cases, including genetic amplification of MYCN and mutations of ALK, ATRX, and PTPN116." (PMID 31819055, 2019). "Chromothripsis events on chromosomes 2, 5, and 17 in neuroblastoma tumors have been previously reported to be associated with MYCN amplification, TERT rearrangements, and 17q gain, respectively." (PMID 31693904, 2019). "Here, we also found that higher Megf6 transcript levels are associated with poor outcome in this neuroblastoma subset, and this is consistent with our RNA-seq data and the delayed tumorigenesis observed in the Th-MYCN/Casp2−/− mouse model." (PMID 30670683, 2019). "To identify genes associated with delayed neuroblastoma development in Th-MYCN/Casp2−/− mice, we examined various molecular biomarkers of neuroblastoma development and prognosis." (PMID 30670683, 2019). "MYCN amplification encoding the transcription factor N-MYC has been documented in most of the malignant neuroblastomas that cover about 20–25% of all NB." (PMID 30691436, 2019).
neuroblastoma (continued). "For example, the MYCN amplification is the most common genomic aberration in high-risk neuroblastoma, which leads to MYCN overexpression, driving aggressive diseases." (PMID 31285550, 2019). "In particular, loss of 1p36 occurs in 20–30% of neuroblastoma cases and correlates with MYCN amplification, whereas loss of 11q23 in occurs in approximately 40% of cases but almost never occurs with MYCN amplification." (PMID 31616462, 2019). "Among them, amplification of the MYCN gene and over-expression of N-Myc protein are the most reliable risk factors in neuroblastoma patients." (PMID 31452837, 2019). "In particular, the unfavorable outcome of neuroblastoma is associated with deletion of chromosomes 1p or 11q, gain of chromosome 17q, or amplification of the MYCN proto-oncogene." (PMID 30609639, 2019). "MYCN-amplification occurs in about 20% of neuroblastomas and is associated with aggressive tumors and poor survival." (PMID 30744170, 2019). "Our analysis identified a 41-gene signature in Th-MYCN/Casp2−/− tumors, associated with neuroblastoma outcome, and involved in altered melanogenesis, Wnt and Hippo pathway signaling." (PMID 30670683, 2019). "MYCN is a transcription factor that plays a key role in a wide variety of phenotypes associated with malignant behavior of neuroblastomas, including metastatic dissemination." (PMID 31293052, 2019). "In childhood neuroblastomas with MYCN gene amplification, DLL1 is highly expressed and implicated in the onset of this type of cancer by promoting cell proliferation and maintaining their undifferentiated status." (PMID 31107884, 2019). "For more than two decades, a number of genetic aberrations closely associated with outcome have been identified in neuroblastoma; for the MYCN gene, these include 17q gain, loss of 3p, and 11q deletion." (PMID 31685009, 2019). "Neuroblastoma patients with the MYCN gene amplification are classified into the high-risk group, and their survival rates remain in the range of 30%–40%, which represents the highest number of cancer-related deaths among pediatric solid cancers." (PMID 31452837, 2019). "Here, we show a strong correlation between high-risk disease, MYCN expression, poor survival, and ribosome biogenesis in neuroblastoma patients." (PMID 30542116, 2019). "In the case of neuroblastoma, tumors with high amplification of MYCN show hyperactivation of PRC2-associated components such as EZH2, EED, and RBBP7 with respect to non-MYCN-amplified neuroblastoma cases." (PMID 31920530, 2019). "Further, PRMT5 is associated with MYCN (another member of the MYC family of transcription factors) in neuroblastoma cells and promotes its stability." (PMID 31694585, 2019). "Amplification of MYCN is a defining feature of high-risk neuroblastoma, which when present at diagnosis, predicts a five-year overall survival of only 50%." (PMID 35582571, 2019). "Overexpression of the AURKA gene in neuroblastoma is associated with high-risk, late-stage tumors, unfavorable histology, MYCN amplification, and in general decreased survival of neuroblastoma patients." (PMID 30027525, 2018). "The remarkable effect on colony formation with a significant reduction in the number of colonies of NGP cells shows a direct, on-target effect in poorly differentiated MYCN-amplified neuroblastoma of poor risk category." (PMID 29515779, 2018). "Regulation of the MRP1 gene at the 5′ untranslated promoter region is associated with various transcription factors, including neuroblastoma-derived MYC (MYCN)." (PMID 30486290, 2018). "There are several factors that define specific cases of neuroblastoma, but high risk ones include stage, age, MYCN oncogene amplification, chromosome 11q status, metastasis, histologic category, and deoxyribonucleic acid (DNA) ploidy." (PMID 30274306, 2018). "Prognosis of neuroblastoma patients is associated with many factors, such as age at diagnosis, tumor stage and oncogene MYCN amplification." (PMID 30012197, 2018).